IL6 (interleukin 6)
Diseases named in the same sentence as IL6 in open-access papers (continued):
Sharing a sentence is not in itself a finding about the gene and the disease.
ischemia (continued). "We found that serum inflammatory cytokines, including IL-6, IL-1β, and TNF-α, were significantly decreased by MLB during hepatic ischemia/reperfusion (I/R) injury, suggesting that MLB may alleviate hepatic I/R injury via inhibiting inflammatory signaling pathways." (PMID 31231218, 2019). "Notably, the degrees of CXC motif chemokine 10 (CXCL10) and interleukin-6 (IL-6) were >20, suggesting they may have an important role in MCAO-induced ischemia." (PMID 25333814, 2015). "Taken together, these findings suggest that, in addition to ischemia, inflammation is involved in the increase of vascular permeability and disruption of the blood-aqueous barrier via release of inflammatory factors (VEGF, IL-6, MCP-1, and sICAM-1) in BRVO patients with macular edema." (PMID 24884703, 2014). "It is hypothesized that next to ischemic myocardium, whole body ischemia, endotoxin translocation from the gut, excessive vasopressor therapy, and noncardiac organ failure are also contributing factors to IL-6 release." (PMID 22889197, 2012). "Our hypothesis is further supported by the evidence that either chemical and ischemic preconditioning was shown to attenuate ischemia-induced mRNA elevations of inflammatory cytokines (i.e., IL-1β and IL-6), while not affecting the elevation of the protective TGF-β occurring in the ischemic cortex." (PMID 35359933, 2022). "This suggests that IL6, which is also believed to have a role in neurodegeneration rather than neuroprotection in cerebral ischemia, is responsive to PACAP38 treatment, which might be one of the mechanisms by which PACAP38 could exert a neuroprotective role in the brain during ischemia." (PMID 25257527, 2014). "Our results indicate that ischemia of the adductor muscle significantly increased levels of TNF-α and IL-6 compared with the NONISCH (P < 0.05)." (PMID 33959422, 2021). "Further dichotomy of patients who developed cerebral ischemia into two sub-groups including ischemia due to intervention (interventional CI) and the second group with delayed cerebral ischemia (DCI), showed that serum IL-6 levels were non-significantly raised later in the interventional CI group." (PMID 29194369, 2017). "We observed in this unique population of women with signs and symptoms of ischemia, non-obstructive CAD and preserved EF at enrollment, IL-6 was the strongest predictor of HF hospitalization in these women compared to hs-CRP and SAA level, especially in the highest quartile (>4.79 pg/mL)." (PMID 28542263, 2017).
injury (261 papers, 2007 to 2025). Damage inflicted on the body as the direct or indirect result of an external force, with or without disruption of structural continuity. "Naringenin have been reported to reduce the expression of signalling molecules such as IL-6, IL-8, inducible nitric oxide synthase (iNOS), and nuclear erythroid-related factor (Nrf2) associated with heart injury." (PMID 40893793, 2025). "Within the study group, females with ALD had significantly greater levels of circulating IL-6 and Treg cells than males, suggesting that an immune difference influences females’ susceptibility to alcohol-associated liver injury." (PMID 38370409, 2024). "In particular, anti-cytokine activity is one of the beneficial effects of therapeutic hypothermia in acute brain injury, and reduction in serum IL-6 and cytokine levels is associated with a better outcome." (PMID 40757726, 2024). "Curiously, IL-6 has also been implicated in the recruitment and activation of microglia after nerve injury, and M-CSF dose-dependently increased the expression of microglial IL-6 mRNA in vitro." (PMID 36830952, 2023). "IL-6, a pro-inflammatory factor is involved in the development of pathological pain associated with inflammation, cancer, and nerve trauma." (PMID 36195881, 2022). "For example, childhood trauma was associated with lower methylation of the proinflammatory IL-6 promoter, and lower methylation in turn was associated with greater salivary IL-6 in response to the Trier Social Stress Test64." (PMID 33608499, 2021). "Liver injury was significantly associated with higher levels of interleukin (IL)-6 and IL-10 (p < 0.05)." (PMID 34307393, 2021). "TNF-α and IL-6 are the important proinflammatory mediators, which are associated with systemic inflammatory response syndrome, acute lung injury, and mortality." (PMID 32082076, 2019). "Activated M1 phenotype microglia produce proinflammatory cytokines such as TNF-α, IL-1β, and IL-6; M2 phenotype microglia produce brain-derived neurotrophic factor and IL-10, which has been associated with neuroprotection after brain injury." (PMID 28529954, 2017). "IL-6 and IL-12 have been reported to be key mediators of acute lung injury in mice while IFN-γ and TNF-α were associated with acute lung injury." (PMID 26136733, 2015). "Plasma levels of IL-6 greater than 100 pg/mL in the first 24 h following injury have been found to be associated with severe brain injury." (PMID 23459929, 2013). "In traumatic brain injury the presence of low concentrations of IL-6 [IL-6 knock-out (KO) mice] is associated with poor behavior performance, and impacts the expression of IL1β, another powerful pro-inflammatory cytokine." (PMID 24133408, 2013). "Moreover, the increased secretion of TNF-α and IL-6 from microglia mimics the events happening in traumatic brain injury and metabolic disorders, which in turn increases the risk of neurodegeneration." (PMID 40760135, 2025). "Furthermore, plasma levels of IL-6 have been also associated with morbidity and mortality in patients with acute lung injury." (PMID 39061002, 2024). "Indeed, the inhibition of IL-1β or IL-6 signalling has demonstrated efficacy in alleviating neuropathic pain caused by nerve injury, underscoring the crucial involvement of IL-1β and IL-6 in the pathogenesis of neuropathic pain." (PMID 38390212, 2024). "Indeed, cytokines such as TNF-α-, NO, interleukin 1beta, IL-6, and IL-10 levels are increased in response to acute liver injury caused by free radical production." (PMID 35684137, 2022). "To identify the potential roles of cytokine-mediated changes on VILI-induced brain injury, we measured amygdalar and hippocampal expressions of inflammatory cytokines, IL-6, IL-1β, and TNF-α, which are implicated in the pathogenesis of acute neuropsychiatric impairments." (PMID 36100846, 2022).
injury (continued). "Following TBI, IL-6 levels increase with peak concentrations of 93 to 269 pg/mL in human serum and IL-6 levels greater than 100 pg/mL in the first 24 h after trauma have been associated with severe brain injury." (PMID 32492963, 2020). "Targeting of IL-6 signaling pathways in injured nerve may provide a novel therapeutic window for treating neuropathic pain associated with nerve injury." (PMID 23953943, 2013). "The suppression of EEG power and fetal movement, which may reflect inhibition of synaptic activity due to increased local cytokine production, were associated with significantly elevated circulating IL-6 levels and neuroinflammation that are characteristic of preterm brain injury." (PMID 32293473, 2020). "The second study is by Kanefsky and colleagues (2019), which further demonstrated that, even within individuals with both PTSD and TBI, the presence of loss of consciousness at the time of the traumatic brain injury may also influence the alteration in proinflammatory cytokine levels of IL-6." (PMID 31991875, 2020). "However, excessive training with insufficient recovery causes musculoskeletal trauma with increased production of pro-inflammatory cytokines such as IL-1β, IL-6, and TNF-α, which contributes to symptoms related to performance decrement and exercise-induced fatigue." (PMID 31616260, 2019). "In a study on the mechanisms of microglia activation via the IL-6 pathway in traumatic brain injury, the authors achieved similar results; therefore, cases of severe CNS injury should be included." (PMID 41465547, 2025). "In this study, treatment with CAG decreased the levels of TNF-α, IL-6, and IL-1β, suppressing inflammatory response and alleviating alcohol-induced liver injury." (PMID 40822494, 2025). "IL6 is a pro‐inflammatory cytokine widely studied as an indicator of systemic inflammation in acute brain injury." (PMID 39853806, 2025). "In cases of acute lung injury, proinflammatory cytokines such as IL-6 and TNF-α stimulate the phosphorylation of VE-cadherin." (PMID 40431442, 2025). "This study established the first evidence of Mxene-bpV’sneuroprotective effects against cerebral ischemia-reperfusion injury via a reduction in the levels of pro-inflammatory cytokines, including IL-1β, IL-6 and TNF-α." (PMID 39073469, 2024). "Even though the IL-6 gene and protein levels have been used as biomarkers for inflammatory responses, the protective effects of IL-6 have been reported in acute lung injury." (PMID 38474386, 2024). "Although IL-6 is primarily viewed as a proinflammatory cytokine promoting renal damage, cell-protective and regenerative effects of IL-6 during kidney injury have been documented as well." (PMID 39723211, 2024). "Recent preclinical studies demonstrate a direct pathological role for the interleukin-6 (IL-6) pathway in mediating structural and functional delirium-like phenotypes in animal models of acute lung injury." (PMID 38778074, 2024). "Considering that IL-6 was not generated from the accumulated neutrophils, we sought other sources of IL-6 during LPS-induced acute lung injury." (PMID 39337592, 2024). "These pathways have been identified as key regulators for the release of various inflammatory mediators, such as tumor necrosis factor alpha (TNF-α) and interleukin-6 (IL-6), which play a vital role in the pathogenesis of acute lung injury." (PMID 37637154, 2023). "Previous research on the APR blend has shown protective effects in a mouse model of LPS-induced acute lung injury, associated with down-regulation of the pro-inflammatory cytokines TNF-α, Interleukin-1 beta (IL-1β), and Interleukin-6 (IL-6)." (PMID 37699014, 2023). "ERK and TLR4 signaling pathways can activate related proteins, leading to the activation of inflammatory factors such as IL-1 and IL-6, with the end result of liver injury." (PMID 37894611, 2023).
injury (continued). "Concurrently, ASD also downregulated the expression levels of MCP-1, TNF-α and IL-6 proteins in mice model of CCl4-induced liver injury, dose-dependently." (PMID 38223644, 2023). "Eugenol (10.7 mg/kg) reduced TNFα and IL-6 plasma levels 48 h after the initiation of thioacetamide-induced liver injury in rats." (PMID 38256335, 2023). "More importantly, PARP-1 activation is uncovered to promote the expression level of IL-6 in LPS-induced acute lung injury, which promotes the differentiation of Th17 cells and reduces the differentiation of Treg cells." (PMID 35190759, 2022). "Among the pro-inflammatory cytokines that trigger the CisPT-mediated pathophysiological developments associated with brain injury; TNF-α and IL-6 are extremely potent as they also stimulate the discharge of other cytokines as well." (PMID 35790919, 2022). "BLM-induced acute lung injury was associated with a significant increase in the mean concentration of TNF-α, IL-6, IL-1B, and NF-kB in lung tissues compared to that in the control (p < 0.05)." (PMID 36500388, 2022). "Reportedly, IL-6 is a representative inflammatory cytokine, and its level is elevated in animal models of alcohol-related liver injury." (PMID 36081800, 2022). "In a study of myocardial ischemia-reperfusion injury, researchers found that Puerarin can reduce the expression of inflammatory cytokines IL-6, IL-1β, and TNF-α through AMPK/Akt/GSK-3β /Nrf2 signaling pathway to prevent myocardial ischemia-reperfusion injury." (PMID 35482440, 2022). "Experimental evidence supports the role of IL-6 in promoting vascular endothelial cell permeability and inflammation, which potentially aggravates acute lung injury." (PMID 34986829, 2022). "Pharmacological inhibition of global IL-6 signaling and IL-6 trans-signaling improved survival and alveolarization in hyperoxia-induced lung injury." (PMID 35251477, 2022). "IL-6 mediates neuroinflammation and contributes to motor coordination deficits after mild traumatic brain injury." (PMID 36142500, 2022). "Our cytokine analysis, using Simoa® technology, demonstrated robust decreases in IL-1β and IL-6, which, in light of the existing literature on head trauma, are quite paradoxical." (PMID 35785366, 2022). "Evidence accumulates that STING pathway is involved in inflammation; for instance, STING-mediated type 1 interferons regulates the elevation of proinflammatory cytokine profile with increased TNF-α, IL-6, and IL-1β in microglia of traumatic brain injury." (PMID 35979145, 2022). "Expressions of TNF-α, IL-1β, IL-6, and IL-8 cytokines in rats with acute lung injury induced by oleic acid were downregulated in the TCZ and DEX groups compared to the OA group (P < 0.05)." (PMID 36115998, 2022). "Whereas most studies generally focus on the use of one cytokine, a few studies have used a combination of TNF-α, IL-6 and soluble IL-6 receptor (sIL-6R) to better simulate the inflammatory environment existing after knee trauma." (PMID 33671471, 2021). "Previous studies have suggested that the levels of tumor necrosis factor α (TNF-α), nuclear factor (NF-κB), interleukin 1β (IL-1β), and IL-6 increase in the bronchoalveolar lavage fluid of experimental rats with acute PQ-induced lung injury." (PMID 34580234, 2021). "The immunomodulatory properties of hAECs likely underlie the beneficial effects of hAECs in large animal models of perinatal lung and brain injury, in which IL-1 and IL-6 expression are reduced." (PMID 34170941, 2021). "In particular, lutein and zeaxanthin reduced cytokines (IL-1β, IL-6) and NF-κB levels probably activating the Nrf2 pathway in a mouse model of traumatic brain injury." (PMID 34206804, 2021). "Interleukin-6 (IL-6) is a pleiotropic pro-inflammatory cytokine as well as a profibrotic factor in bleomycin (BLM)-induced lung injuries." (PMID 32587955, 2020). "VC decreases IL-4, IL-6 and IL-8 level via inhibition of NF-κB signaling pathway in concanavalin A- induced liver injury mice." (PMID 32344708, 2020).
injury (continued). "RosA significantly reduced LPS-induced TNF-α, IL-6, and IL-1β production; RosA plays an anti-inflammatory effect on the acute lung injury in mice by inhibiting ERK/MAPK signaling in a dose-dependent manner." (PMID 32184728, 2020). "Studies on patients with brain injury showed that IL-6 levels were high within a few hours after brain injury and that they gradually decreased after 1–2 days." (PMID 33392188, 2020). "In myocardial injury patients, corticosteroid therapies had markedly decreased the blood levels of IL-6 [6.0 (4.9–7.6) vs. 15.4 (5.8–34.9) pg/mL; P = 0.03] as well as the incidence of in-hospital adverse events [1/17 (5.9%) vs. 11/29 (37.9%); P = 0.034]." (PMID 33505992, 2020). "Sesamol also reduced inflammatory cell secretions of TNF-α and IL-6, promoted superoxide dismutase expression to increase antioxidation effects, and reduced neutrophil infiltration in a rat model of LPS-induced acute lung injury." (PMID 32244835, 2020). "Stimulating cells with either IL-1β or sera from trauma patients induced a strong release of IL-6 as well as increased neutrophil adhesion to epithelial cells." (PMID 31739600, 2019). "Inflammatory cytokines such as TNF-α and IL-6 play essential roles in the pathogenesis of ConA-induced liver injury." (PMID 30622431, 2018). "Proinflammatory cytokines such as IL-6, have been reported with their upregulating effect following nerve injury (Lee, Lee, Son, Hwang, & Cho, 2004)." (PMID 30519383, 2018). "In mice, levels of TNF-α, IL-1β, and IL-6 show an early rise (peaking at 2–4 h after aggression) in a lipopolysaccharide-induced lung injury model." (PMID 29515461, 2018). "PQ activates the NF-κB signaling pathway, resulting in the release of TNF-α, IL-1β, and IL-6 and leading to acute lung injury." (PMID 29566055, 2018). "We evaluated TNF-α, IL-6, and IL-1β, the major mediators in ConA-induced liver injury, and found that their expression was consistent with the extent of necrosis, apoptosis, and autophagy." (PMID 30116260, 2018). "Deficits in motor coordination have been shown to be mediated by increased IL-6 levels in mice with mild traumatic brain injury." (PMID 29018327, 2017). "In our previous studies, we have demonstrated important roles of oxidative stress, neutrophil activation, adhesion molecules, and pro-inflammatory cytokines, such as IL-1 and IL-6 in smoke inhalation-induced acute lung injury in sheep model." (PMID 28982177, 2017). "It has been shown that various inflammatory cytokines, such as IL-1β and IL-6, produced during drug-induced liver injury are involved in promoting further liver tissue damage, so we next evaluated serum levels of IL-1β and IL-6." (PMID 28481246, 2017). "Studies have confirmed that maresin 1 can suppress neutrophil infiltration and adhesion and reduce proinflammatory mediators such as TNF-α, IL-1β, and IL-6 in mice induced by acute lung injury." (PMID 28182085, 2017). "I3C was found to reduce cellular infiltration into the broncho-alveolar lavage fluid (BALF) of LPS-induced acute lung injury, while also decreasing proinflammatory cytokines, such as IL-6 and TNF-α, in the lungs." (PMID 25706292, 2015). "This interaction of TLR4 and MyD88 triggers the downstream signaling cascade leading to the activation of the nuclear factor κB (NF-κB) pathway, further releasing inflammatory cytokines such as TNF-α and IL-6, which, in turn, can result in liver injury." (PMID 25328713, 2014). "It is known that an increase in the level of pro-inflammatory cytokines, including TNF-α and IL-6, is an early feature of acute lung injury induced by clinical and experimental I/R." (PMID 24345905, 2014). "In CSF, increases in IL-6 protein can be detected within 1 h, with peak expression between 2 and 5 h after an experimental brain injury." (PMID 23459929, 2013).